PEG3 (paternally expressed 3)
Description:
Induces apoptosis in cooperation with SIAH1A. Acts synergistically with TRAF2 and inhibits TNF induced apoptosis through activation of NF-kappa-B (By similarity). Possesses a tumor suppressing activity in glioma cells.
Synonyms: KIAA0287; ZSCAN24; ZKSCAN22; ZNF904; PW1
Tractability: PROTAC: ubiquitination databases record sites on it.
Gene: Protein-coding gene on chromosome 19 (56,810,077 to 56,840,728, reverse strand). Ensembl gene ENSG00000198300.
Subcellular location: Nucleus; Cytoplasm
Subcellular location (Human Protein Atlas): Nucleoplasm
Gene Ontology:
Molecular function: protein binding; DNA-binding transcription factor activity, RNA polymerase II-specific; RNA polymerase II transcription regulatory region sequence-specific DNA binding
Biological process: negative regulation of transcription by RNA polymerase II; positive regulation of transcription by RNA polymerase II; regulation of gene expression; regulation of transcription by RNA polymerase II
Cellular component: autophagosome; nucleus; cytoplasm
Genetic constraint (gnomAD): Loss-of-function variants: 23 observed, 37.52 expected, observed/expected ratio (o/e) 0.61, 90% interval 0.44 to 0.87. The upper end of that interval is the gene's LOEUF score, 0.87, which puts it in group 3 of 6, group 1 being the genes least tolerant of losing a copy. Missense variants: 1,960 observed, 2,087.5 expected, observed/expected ratio (o/e) 0.94, 90% interval 0.9 to 0.98. Synonymous variants: 707 observed, 734.38 expected, observed/expected ratio (o/e) 0.96, 90% interval 0.9 to 1.02.
Homologues: Orthologues: chimpanzee PEG3 (91% identical), macaque PEG3 (87% identical), rabbit PEG3 (80% identical), dog PEG3 (74% identical), rat Peg3 (67% identical), mouse Peg3 (65% identical), pig PEG3 (58% identical), Drosophila melanogaster hb (6% identical), Drosophila melanogaster CG12391 (5% identical), zebrafish plagl2 (5% identical), Caenorhabditis elegans hbl-1 (4% identical), zebrafish plagx (4% identical), and 4 more. Paralogues in human: ZNF518A (8% identical), ZNF518B (6% identical), REST (6% identical), ZKSCAN2 (6% identical), ZNF18 (6% identical), ZNF274 (6% identical), ZNF770 (6% identical), ZSCAN29 (6% identical), ZBTB35 (6% identical), ZNF202 (6% identical), ZSCAN32 (5% identical), ZNF496 (5% identical), and 17 more.
Diseases named in the same sentence as PEG3 in open-access papers:
PEG3 is named in the same sentence as 59 diseases in open-access papers, as found by Europe PMC text mining. Sharing a sentence is not in itself a finding about the gene and the disease. The quoted sentences say what the papers report.
Obesity (12 papers, 2013 to 2022). Accumulation of substantial excess body fat. "Human genetic variants near NNAT associate in some populations with NNAT expression and with obesity, also in children, and paternal transmission of obesity in F1 background crosses has been associated with Peg3 variation." (PMID 26824653, 2016). "Our findings suggest that down-regulation of Peg3 and Igf2 in adipocytes contributes to diet-induced obesity and the symptoms associated with obesity." (PMID 24416415, 2014). "Studies also show paternal gene imprinting of alleles related to body fat accumulation, Igf2 and Peg3, to be decreased in obesity-resistance mice compared to obesity-prone mice, suggesting a likelihood of paternal gene transmission in offspring resulting in diet-induced obesity." (PMID 33324346, 2020). "Down-regulation of Peg3 and Igf2 in adipocytes could contribute to diet-induced obesity and the symptoms associated with obesity." (PMID 24416415, 2014). "In addition to fat gain, Peg3 and Igf2 might also contribute to the symptoms associated with obesity." (PMID 24416415, 2014). "Obesity also results from deletion of paternally expressed genes, Peg3, Pref1/Dlk1, or Magel2 with observed differences in hyperphagia and energy expenditure, all of which demonstrate catch up growth in null mice." (PMID 30279096, 2018). "We previously demonstrated a negative correlation between paternal transmission of HFD-induced obesity and expression of two imprinted genes, Igf2 and Peg3 (paternal expressed gene, PEG)." (PMID 26868178, 2016). "The other upregulated gene, PEG3, encodes a C2H2 type zinc finger protein implicated in regulation of body temperature, feeding behavior, and obesity, as well as growth, apoptosis, and maternal nurturing behavior." (PMID 25572662, 2015). "This study reports evidence for a paternal transmission of HFD-induced obesity and a correlated expression of Igf2 and Peg3 (paternal expressed gene 3) imprinted genes." (PMID 24416415, 2014). "In this study, we report evidence for paternal transmission of HFD-induced obesity, which correlated with the expression of Peg3 and Igf2 imprinted genes." (PMID 24416415, 2014). "In the present study, we found the DNA methylation patterns at the DMRs of H19 and Peg3 in spermatozoa of offspring were influenced by pre-existing maternal diabetes and obesity, respectively." (PMID 24721882, 2014). "We previously demonstrated a negative correlation between paternal transmission of HFD-induced obesity and expression of two PEGs, Igf2 and Peg3, suggesting that these genes might contribute to fat accumulation, or the symptoms associated with obesity." (PMID 26868178, 2016). "Several imprinted genes are associated with body weight dysregulation, and we found that Peg3 and Igf2 might be involved in the paternal transmission of propensity to diet-induced obesity." (PMID 24416415, 2014). "In conclusion, we report that HFD-induced obesity is paternally transmitted and is correlated with expression of the Peg3 and Igf2 imprinted genes, and that down-regulation of Peg3 and Igf2 in adipocytes can contribute to diet-induced obesity and the symptoms associated with obesity." (PMID 24416415, 2014). "Taken together, our findings suggest that the down-regulation of Igf2 and Peg3 imprinted genes in adipocytes may be involved in the paternal transmission of HFD-induced obesity." (PMID 24416415, 2014). "Old BAT showed decreased gene expression related to the lipid metabolism, such as stearoyl-CoA desaturase 2 (Scd2) and angiopoietin-like 8 (Angptl8), and increased gene expression related to obesity in WAT, such as Peg3." (PMID 34884947, 2021). "Therefore, the down-regulation of Peg3 and Igf2 and up-regulation of Igf2r in adipocytes from HFD-induced obesity mice is specific to B6 mice." (PMID 24416415, 2014).
Obesity (continued). "Interestingly, Igf2 and Peg3, which are paternally expressed imprinted genes involved in the regulation of body fat accumulation, were down-regulated in B6 and (PWK×B6) F1 mice, which are susceptible to HFD-induced obesity, but not in PWK and (B6×PWK) F1 mice, which are resistant." (PMID 24416415, 2014).
breast carcinoma (8 papers, 2012 to 2025). "In breast cancer, PEG3 mutation was associated with a high tumor mutation burden and an inferior prognosis." (PMID 36451866, 2022). "We previously discovered that systemic delivery of decorin for treatment of breast carcinoma xenografts induces paternally expressed gene 3 (Peg3), an imprinted gene encoding a zinc finger transcription factor postulated to function as a tumor suppressor." (PMID 28174297, 2017). "The downstream function of either Peg3 or mitostatin in response to decorin manifests as potent means to subdue breast cancer development and progression." (PMID 35159071, 2022). "Soluble decorin evokes protracted endothelial cell autophagy via Peg3 and breast carcinoma cell mitophagy via mitostatin by interacting with VEGFR2 or the MET receptor tyrosine kinase, respectively." (PMID 35159071, 2022). "PEG3 was previously reported as tumor suppressor in various cancers, including lung cancer and breast cancer." (PMID 36451866, 2022). "To further strengthen the in vivo relevance of our data, we determined the expression of Peg3 and Bmp2k in the same orthotopic mammary tumor xenografts as used above." (PMID 23029096, 2012). "Given the role of Peg3 as a tumor suppressor gene in breast cancer and its roles in autophagy, Peg3 may subsume an important regulatory function connecting mitostatin/Parkin to the mitophagy system." (PMID 35159071, 2022). "Also, Peg3 is a well-known tumor suppressor, and its promoter region is usually hypermethylated in the patients of ovarian and breast cancers." (PMID 30216384, 2018). "Similarly, LOI resulting in biallelic silencing of genes like PEG3, P57, and IGF2R has been observed in oligodendrogliomas, breast cancer, and hepatocellular carcinomas, respectively." (PMID 39941009, 2025). "However, the associations of PEG3 mutation with tumor mutation burden (TMB) and prognosis in breast cancer have not been investigated." (PMID 32729618, 2020). "Importantly, we demonstrate a reproducible induction of a presumed tumor suppressor gene (Peg3) within the stromal compartment as well as implicating a novel role for Bmp2k in breast cancer samples." (PMID 23029096, 2012).
glioma (8 papers, 2013 to 2023). A benign or malignant brain and spinal cord tumor that arises from glial cells (astrocytes, oligodendrocytes, ependymal cells). "In fact, re-expression of Peg3 in ovarian and glioma cell lines suppresses tumorigenicity in vitro and in vivo." (PMID 28174297, 2017). "In glioma cell lines, reintroducing Peg3 abrogates Wnt signaling by promoting degradation of β-catenin via the proteasome in a non-canonical pathway that is independent of glycogen synthase kinase 3β." (PMID 28174297, 2017). "In addition, Pw1/Peg3 has been described as a tumor suppressor in glioma cell lines and human ovarian cancer." (PMID 30279563, 2018). "Notably, reintroduction of Peg3 into glioma xenografts inhibits tumor growth, suggesting that Peg3 functions as a tumor suppressor." (PMID 28174297, 2017). "Alterations in CDK4/6, CIC, FGFR2/3/4, FUBP1, KIT, MET, NF1, PEG3, RB1, and NTRK2 were additional factors correlated with the survival of different subtypes of gliomas." (PMID 36998447, 2023). "Growing studies have focused on the role of microRNA-21 (miR-21) in glioma, thus our objective was to discuss the effect of M2 bone marrow-derived macrophage (BMDM)-derived exosomes (BMDM-Exos) shuffle miR-21 on biological functions of glioma cells by regulating paternally expressed gene 3 (PEG3)." (PMID 32231463, 2020). "Among these, the expression of BAI3, PEG3, SNCA has already been reported to be absent or significantly decreased in GBM and glioma cells." (PMID 23472076, 2013).
Anxiety (5 papers, 2012 to 2024). Intense feelings of nervousness, tension, or panic often arise in response to interpersonal stresses. "We have experimentally demonstrated that Peg3 deficiency confined to the offspring causes anxiety in mouse mothers and atypical behaviour including deficits in communication in their male offspring." (PMID 38595977, 2024). "Given that all dams were genetically WT, these results further demonstrate that maternal anxiety traits are caused by the reduced dosage of Peg3 in the offspring." (PMID 38595977, 2024). "Specifically, WT dams carrying and caring for litters consisting entirely of Peg3-deficient pups exhibit enhanced maternal novelty reactivity during pregnancy and, postpartum, delayed sniffing and retrieval of their pups, alongside anxiety-like behaviours." (PMID 38595977, 2024). "In this study, we reproduced our original finding that WT dams carrying and caring for Peg3-deficient offspring were slower to retrieve their mutant pups and exhibited increased anxiety-like behaviour compared to WT dams with WT pups demonstrating the robustness of this finding." (PMID 38595977, 2024). "Therefore, it is possible that the reduced USV production associated with a null mutation in offspring Peg3 increases maternal anxiety in the post-natal period as well as reducing pup retrieval." (PMID 29186532, 2018). "Taken together, these data suggest a functional role for reduced Peg3 dosage in the offspring in influencing maternal behaviour, with important relevance for maternal post-natal anxiety." (PMID 29186532, 2018). "Given the finding that the dosage of Peg3 in the offspring also influences maternal anxiety-like behaviour, it is possible that reduced expression of PEG3 in human offspring underlies the co-occurrence of maternal mood disorders and atypical male-specific behaviours observed in human children." (PMID 38595977, 2024). "Interestingly, LG/J mothers exhibit many of the same maternal care impairments observed in Peg3 knockout females, including deficits in pup retrieval, milk ejection, locomotion, and an increase in anxiety-like behaviors." (PMID 22950040, 2012). "Interestingly, our results are broadly similar to those obtained in a study of the effects of a single imprinted gene knockout, in which wild-type mothers of Peg3 knockout litters did not exhibit altered anxiety-like behaviour prepartum but were slower to retrieve neonates." (PMID 31598302, 2019).
depression (4 papers, 2016 to 2024). "We recently reported reduced expression of the human PEG3 gene in the placenta from women with either diagnosed depression in pregnancy or questionnaire determined depressive symptoms." (PMID 30320110, 2018).
intrauterine growth restriction (4 papers, 2015 to 2022). "Reduced expression of Peg3 in mice has also been linked to fetal growth restriction." (PMID 27523184, 2016). "In mice, ART treatment resulted in small changes in methylation of control-region CpGs for H19, IGF2R, and PEG3, altered expression of these genes, and intrauterine growth restriction (IUGR)." (PMID 36142363, 2022). "Gene expression studies, without correlation to their imprinting status, have demonstrated upregulation of PEG3 (as well as several other genes) in intrauterine growth restriction (IUGR) placentas." (PMID 25806045, 2015).
lung carcinoma (4 papers, 2015 to 2025). "Our analysis on the whole transcriptome integrated with TCGA datasets on human lung cancer revealed that EGCG reverses the lung carcinogenesis-associated changes of Myb and Peg3, suggesting that Myb and Peg3 play key roles in the anti-cancer activity of EGCG." (PMID 27461468, 2016). "These gene pairs were distinct across cancer types in general, but some simultaneously occurred in different cancers, e.g., NFATC4/FAT1 appeared in both endometrial and lung cancers and PEG3/ZIM2 appeared in skin and esophageal cancers." (PMID 26212640, 2015). "Knockdown of 16 of 18 (89%) CPD genes reduced viability in both cell lines —including five targets not previously implicated in lung cancer (Ephx2, Peg3, Apob, Oit1 and Slc6a19)." (PMID 40825871, 2025).
ovarian carcinoma (3 papers, 2010 to 2021). A malignant neoplasm originating from the surface ovarian epithelium. "In this light, downregulation of the imprinted growth-inhibitory genes Aplasia Ras homologue member I (ARHI) and paternally expressed 3 (PEG3) may be particularly important in the pathogenesis of ovarian cancer." (PMID 22481926, 2012). "We analysed the expression of frequently downregulated tumour suppressor genes in immune subtype (ie DIRAS3, PEG3, and DLEC1) in the human ovarian cancer cell line SKOV3 and found DIRAS3 was most highly expressed." (PMID 33522069, 2021). "For example, in ovarian cancer it is accompanied by sharp downregulation of genes COLEC11, PEG3 and TSPAN8, which is not the case in other cancers." (PMID 21047417, 2010).
prostate carcinoma (3 papers, 2016 to 2019). A carcinoma that arises from epithelial cells of the prostate gland. "This function of the transcription factor “PEG3” is relevant to prostate cancer." (PMID 28148240, 2017).
rhabdomyosarcoma (3 papers, 2013 to 2023). A rare aggressive malignant mesenchymal neoplasm arising from skeletal muscle. "In concordance with our finding, higher PEG3 mRNA level was also found in various embryonal cancers (such as rhabdomyosarcoma, medullablastoma and Wilm’s tumors) compared with non-embryonal cancers (acute lymphoblastic leukemia and osteosarcoma) and non-cancerous tissues." (PMID 28471449, 2017). "A subset (MEST, PLAGL1, PEG3, DLK1, IGF2) showed elevated expression in various embryonal cancers, especially rhabdomyosarcoma, as compared to non-embryonal cancers and normal tissues." (PMID 36437415, 2023).
behavioural disorders (2 papers, 2018 to 2024). "Peg3 deficiency could drive the association of maternal and offspring behavioural disorders reported in humans." (PMID 38595977, 2024). "Together, these data suggest Peg3 as a promising candidate for human behavioural disorders." (PMID 29186532, 2018).
Cachexia (2 papers, 2009 to 2010). Severe weight loss, wasting of muscle, loss of appetite, and general debility related to a chronic disease.
diabetes (2 papers, 2014 to 2016). "The samples of Peg3 were all uncut by both enzymes in the two groups, suggesting that the methylation pattern of Peg3 in spermatozoa of OD was not affected by maternal diabetes." (PMID 24721882, 2014).
germ cell testicular tumors (2 papers, 2017 to 2018). "In human testicular germ cell tumor, loss of miR-514a-3p upregulated paternally expressed gene 3 (PEG3) and consequently overexpressed PEG3 recruited TRAF2 to activate the NF-κB pathway." (PMID 29616037, 2018). "Strong nuclear p50 and PEG3 expressions were observed in different subtypes of TGCTs, whereas their expressions were lower in non-germ cell testicular tumors and testicular non-tumor tissues." (PMID 28471449, 2017).
glioblastoma (2 papers, 2023). The most malignant astrocytic tumor (WHO grade IV). "In the overlap analysis, we found the overexpression of ABCA13, PEG3, and SOX4 that have been shown to be poor prognostic markers in other cancers including ovarian, glioblastoma, and colon." (PMID 37370820, 2023). "The alterations in FGFR4, KIT, and PEG3 were correlated with a short OS in astrocytoma, alterations in CDK4, FUBP1, and NTRK2 were correlated with a short OS in oligodendroglioma, and alterations in CDK4, CIC, FGFR3, and KMT5B were correlated with a short OS in glioblastoma." (PMID 36998447, 2023).
Insulin resistance (2 papers, 2022 to 2023). Increased resistance towards insulin, that is, diminished effectiveness of insulin in reducing blood glucose levels. "PEG3 deficiency promotes male-specific accelerated adiposity, diabetic-like insulin resistance and fatty liver." (PMID 37152245, 2023). "As a result, Pw1/Peg3 deficient mice develop a sex-dependent global shift of body metabolism towards accelerated adiposity, diabetic-like insulin resistance, and fatty liver." (PMID 35025875, 2022).
muscular dystrophies (2 papers, 2015 to 2016). "We conclude that PW1/Peg3 function is essential for conferring proper mesoangioblast competence and that the determination of PW1/Peg3 levels in human mesoangioblasts may serve as a biomarker to identify the best donor populations for therapeutic application in muscular dystrophies." (PMID 25751651, 2015).
myocardial infarction (2 papers, 2020 to 2022). Gross necrosis of the myocardium, as a result of interruption of the blood supply to the area, as in coronary thrombosis. "We have recently shown that cardiac fibrosis post-myocardial infarction (MI) can be regulated by resident cardiac cells with a fibrogenic signature and identified by the expression of PW1 (Peg3)." (PMID 32647159, 2020).
pancreatitis (2 papers, 2024 to 2025). Inflammation of the pancreas.